MTURN (maturin, neural progenitor differentiation regulator homolog)
Description:
Promotes megakaryocyte differentiation by enhancing ERK and JNK signaling as well as up-regulating RUNX1 and FLI1 expression. Represses NF-kappa-B transcriptional activity by inhibiting phosphorylation of RELA at 'Ser-536'. May be involved in early neuronal development (By similarity).
Synonyms: C7orf41; FLJ25903; Ells1
Tractability: PROTAC: ubiquitination databases record sites on it; its protein half-life has been measured.
Gene: Protein-coding gene on chromosome 7 (30,134,986 to 30,162,765, forward strand). Ensembl gene ENSG00000180354.
Subcellular location: Cytoplasm
Subcellular location (Human Protein Atlas): Cytosol
Gene Ontology:
Molecular function: protein binding
Biological process: positive regulation of ERK1 and ERK2 cascade; positive regulation of JNK cascade; positive regulation of megakaryocyte differentiation; regulation of signaling
Cellular component: cytoplasm
Genetic constraint (gnomAD): Loss-of-function variants: 7 observed, 11.46 expected, observed/expected ratio (o/e) 0.61, 90% interval 0.35 to 1.15. The upper end of that interval is the gene's LOEUF score, 1.15, which puts it in group 5 of 6, group 1 being the genes least tolerant of losing a copy. Missense variants: 151 observed, 141.02 expected, observed/expected ratio (o/e) 1.07, 90% interval 0.94 to 1.23. Synonymous variants: 69 observed, 59.23 expected, observed/expected ratio (o/e) 1.16, 90% interval 0.96 to 1.42.
Homologues: Orthologues: chimpanzee MTURN (100% identical), pig MTURN (100% identical), mouse Mturn (98% identical), dog MTURN (97% identical), rat Mturn (95% identical), tropical clawed frog mturn (92% identical), zebrafish mturn (78% identical), macaque MTURN (77% identical), guinea pig MTURN (63% identical).
Diseases named in the same sentence as MTURN in open-access papers:
MTURN is named in the same sentence as 6 diseases in open-access papers, as found by Europe PMC text mining. Sharing a sentence is not in itself a finding about the gene and the disease. The quoted sentences say what the papers report.
lung carcinoma (5 papers, 2021 to 2025). "MTURN (Maturin), a neural progenitor differentiation regulator, was recently implicated in platelet-derived mRNA signatures for lung cancer diagnosis." (PMID 40559081, 2025). "Of the three mRNAs, platelet MTURN mRNA showed high diagnostic efficiency in female patients with lung cancer (AUC 0.825)." (PMID 33219615, 2021). "A panel of three‐platelet mRNAs, namely MAX, MTURN, and HLA‐B, was selected by microarray and validated by qRT–PCR as a biomarker in lung cancer." (PMID 33219615, 2021). "Although not widely studied in NSCLC, MTURN has been implicated in blood-based mRNA signatures for lung cancer detection, particularly in platelet-derived RNA profiles." (PMID 40559081, 2025).
myelocytic leukemia (1 paper, 2019). "12‐O‐tetradecanoylphorbol‐13‐acetate (TPA) is an effective cancer therapeutic reagent for myelocytic leukemia patients, and MTURN is TPA‐responsive and may promote both leukemic and normal megakaryocyte differentiation." (PMID 30924596, 2019).
tumor (4 papers, 2017 to 2022). "Compared with A375 cells, A375 xenograft tumor displayed an upregulation for glial and neuronal genes (GFAP, BDNF, MAP2, MTURN, ROBO2, SYT1 and TUBB3) and neural stemness genes (ASCL1, MSI1, PAX6, PDGFRA, SOX9, VIM, ZIC1/2)." (PMID 33468253, 2021).
cancer (2 papers, 2019 to 2025). A tumor composed of atypical neoplastic, often pleomorphic cells that invade other tissues. "Other genes, such as PREPL (prolyl endopeptidase-like—usually involved in neurological and metabolic pathways) and MTURN (a neural progenitor differentiation regulator associated with cancer progression), emerged as potential biomarkers influencing survival outcomes." (PMID 40559081, 2025). "MTURN is a neural differentiation regulator with emerging roles in cancer biology." (PMID 40559081, 2025).
MTURN also shares sentences with these, for which no sentence is quoted: heart failure (1 paper); small cell lung carcinoma (1).